POLE4 (DNA polymerase epsilon 4, accessory subunit)
Description:
Accessory component of the DNA polymerase epsilon complex. Participates in DNA repair and in chromosomal DNA replication (By similarity).
Synonyms: p12; YHHQ1
Tractability: PROTAC: ubiquitination databases record sites on it; its protein half-life has been measured.
Gene: Protein-coding gene on chromosome 2 (74,958,643 to 74,970,128, forward strand). Ensembl gene ENSG00000115350.
Subcellular location: Nucleus
Subcellular location (Human Protein Atlas): Nucleoplasm; Cytosol
Pathways (Reactome):
DNA Repair: Dual Incision in GG-NER; Dual incision in TC-NER; Gap-filling DNA repair synthesis and ligation in GG-NER; Gap-filling DNA repair synthesis and ligation in TC-NER; HDR through Homologous Recombination (HRR); PCNA-Dependent Long Patch Base Excision Repair; Recognition of DNA damage by PCNA-containing replication complex; Termination of translesion DNA synthesis
DNA Replication: Activation of the pre-replicative complex; DNA replication initiation
Gene Ontology:
Molecular function: protein binding; DNA-directed DNA polymerase activity; protein heterodimerization activity
Biological process: DNA-templated DNA replication; DNA biosynthetic process
Cellular component: ATAC complex; epsilon DNA polymerase complex; nucleoplasm; nucleus
Genetic constraint (gnomAD): Loss-of-function variants: 9 observed, 6.6 expected, observed/expected ratio (o/e) 1.36, 90% interval 0.8 to 1.91. That is too few expected variants to judge how well the gene tolerates losing a copy. Missense variants: 145 observed, 74.43 expected, observed/expected ratio (o/e) 1.95, 90% interval 1.67 to 1.99. Synonymous variants: 68 observed, 41.8 expected, observed/expected ratio (o/e) 1.63, 90% interval 1.33 to 1.92.
Homologues: Orthologues: macaque POLE4 (99% identical), chimpanzee POLE4 (97% identical), dog POLE4 (95% identical), guinea pig POLE4 (95% identical), mouse Pole4 (93% identical), pig POLE4 (92% identical), rat Pole4 (92% identical), zebrafish pole4 (62% identical), Drosophila melanogaster PolE4 (37% identical), Caenorhabditis elegans pole-4 (35% identical). Paralogues in human: NFYC (35% identical), DRAP1 (22% identical).
Diseases named in the same sentence as POLE4 in open-access papers:
POLE4 is named in the same sentence as 21 diseases in open-access papers, as found by Europe PMC text mining. Sharing a sentence is not in itself a finding about the gene and the disease. The quoted sentences say what the papers report.
lymphoma (3 papers, 2018 to 2023). A malignant (clonal) proliferation of B- lymphocytes or T- lymphocytes which involves the lymph nodes, bone marrow and/or extranodal sites. "Pole4 deficiency did not lead to a reduction in lifespan but did result in increased incidence of lymphomas in the thymus (around 12% of Pole4-deficient mice compared to 4% WT mice) and mesenteric lymph nodes (23.5% in Pole4−/− versus 7.7% in WT)." (PMID 29754823, 2018). "Moreover, POLE4-deficient mice have been reported to have severe developmental abnormalities, T/B lymphocytopenia, and lymphoma formation." (PMID 37166429, 2023). "Coupled with observations that Pole4−/− mice, which lack a small subunit of Pol ε (Pole4) that helps facilitate holoenzyme processivity, develop increased lymphomas, these observations suggest a possible link between POLE depletion and tumor development." (PMID 37388540, 2023).
lymphopenia (3 papers, 2018 to 2022). Reduction in the number of lymphocytes. "We previously showed that loss of the POLE4 subunit of Polε leads to a complex developmental condition in mice characterized by reduced growth, craniofacial anomalies, and lymphopenia in association with increased lymphoma predisposition." (PMID 35649380, 2022). "At the organismal level, Pole4-deficient mice suffer from intra- and extra-uterine growth retardation, severe developmental abnormalities, lymphopenia, and lymphomagenesis." (PMID 29754823, 2018). "Genetic ablation of Pole4 in mice leads to a multifaceted disorder characterized by reduced growth, developmental abnormalities, lymphopenia, and increased lymphomagenesis, which resembles IMAGe syndrome in patients affected by hypomorphic mutations of POLE." (PMID 35649380, 2022). "We recently reported the generation of a Pole4 knockout mouse, which presents with intra- and extra-uterine growth restriction, developmental abnormalities, and lymphopenia." (PMID 32460026, 2020). "Since intra-uterine growth retardation and marked reduction in postnatal size and lymphopenia are also seen in the Pole4 mouse model, we hypothesized that this model would help in understanding the human disease pathogenesis." (PMID 29754823, 2018).
anemia (2 papers, 2018). A reduction in the number of red blood cells, the amount of hemoglobin, and/or the volume of packed red blood cells. "Analysis of hematological parameters showed that Pole4-deficient mice exhibit leukopenia, with a 2.3-fold decrease in the number of white blood cells, moderate anemia, and thrombocytosis." (PMID 29754823, 2018). "In addition to this, Pole4−/− mice also showed modest anemia, associated with thrombocytosis, which strongly suggests skewed lineage commitment of the hematopoietic stem cell compartment." (PMID 30217558, 2018).
Fanconi anaemia (2 papers, 2022 to 2025). "Besides ABCC4, POLE3, POLE4, and the Fanconi anemia pathway genes FANCF and C17orf70 are top candidates that sensitize both wild-type and TDP1-KO cells to CPT treatment." (PMID 35869071, 2022).
lung cancer (2 papers, 2024). A malignant neoplasm involving the lung. "Genetic deletions of POLE4 have been identified in cases of malignant mesothelioma and non–small cell lung cancer." (PMID 38828775, 2024). "For example, an RS signature including genes involved in DNA polymerases (POLA1, POLD4, POLE4) was found to be predictive for ATRi response in lung cancer preclinical models." (PMID 38555285, 2024).
glioblastoma (1 paper, 2023). The most malignant astrocytic tumor (WHO grade IV). "Among these patients, WWOX may be inaccessible for its partners and does not manifest its anti-cancer activity, which was proposed in the literature but not regarding glioblastoma or concerning POLE4 and HSF2BP." (PMID 37781246, 2023).
head and neck cancer (1 paper, 2016). A primary or metastatic malignant neoplasm affecting the head and neck. "Elevated levels of POLE4 and other DNA repair genes have been associated with shorter time to melanoma relapse, and in previous studies we identified POLE4 as a putative miR-7-5p target gene in lung and head and neck cancer cell lines." (PMID 27203220, 2016).
immunodeficiencies (1 paper, 2022). "By performing HU-EdU-seq, we observed that Pole4-deficient lymphocytes presented inefficient replication origin activation, independent of their genomic location, pointing to impaired origin activation as the primary pathogenetic mechanism at the basis of these immunodeficiencies." (PMID 35649380, 2022).
leukopenia (1 paper, 2018). "Here, we report that POLE4 deficiency in mice destabilizes the entire Polε complex, leading to embryonic lethality in inbred strains and extensive developmental abnormalities, leukopenia, and tumor predisposition in outbred strains." (PMID 29754823, 2018).
melanoma (1 paper, 2016). A malignant, usually aggressive tumor composed of atypical, neoplastic melanocytes. "Most notably, we report that high expression of specific protein 1 (SP1) and polymerase (DNA-directed), epsilon 4, accessory subunit (POLE4) was associated with significantly worse overall survival in the TCGA melanoma cohort." (PMID 27203220, 2016). "Comparisons across these four datasets showed high expression of either RelA (consensus HR = 1.47), POLE4 (consensus HR = 1.39) or SP1 (consensus HR = 1.48) was consistently associated with an increased risk of death in melanoma." (PMID 27203220, 2016). "Together, our findings suggest that SP1 and POLE4 could represent additional functional targets of miR-7-5p in melanoma, emphasizing the coordinate manner in which miRNAs suppress expression of multiple target genes to exert their biological effects." (PMID 27203220, 2016). "Further, aberrant expression of some of these genes including RelA, POLE4 and SP1 had prognostic implications in terms of melanoma patient survival." (PMID 27203220, 2016).
Obesity (1 paper, 2022). Accumulation of substantial excess body fat. "Comparing the body weight of AAV-injected Sim1-cre mice versus AAV-injected wild-type littermates, we found that overexpression of Snca and Igsf8 caused an exacerbation of HFD-induced obesity, whereas overexpression of Spata2, Pole4, Fndc4, Smim12, or Arrb1 had no impact on body weight." (PMID 36175420, 2022).
Pca (1 paper, 2023). "By combining both KEGG analysis and GO term analysis, seven genes (RNASEH2A, RFC2, RFC4, LIG1, POLD1, POLD2, and POLE4) were identified as new biomarker genes upregulated in CRPC compared to localized Pca and associated with DNA replication and DNA repair." (PMID 37950047, 2023). "We identified six DDR-related genes (Ribonuclease H2 Subunit A (RNASEH2A), replication factor C subunit 2 (RFC2), RFC4, DNA Ligase 1 (LIG1), DNA polymerase D1 (POLD1), and DNA polymerase E4 (POLE4)) that were upregulated in CRPC compared with Pca tissues." (PMID 37950047, 2023).
Sepsis (1 paper, 2022). Sepsis is defined as life-threatening organ dysfunction caused by a dysregulated host response to infection. "Meanwhile, the present study identified eight metabolism-related genes (NME1, NME6, POLD4, POLE4, POLR2J, POLR2L, ADCY3, and ENTPD1) in patients with sepsis and the identified metabolism-related genes may represent diagnostic and therapeutic biomarkers of sepsis." (PMID 35265105, 2022). "However, the exact role of POLE4 in the pathophysiology of sepsis remains unclear." (PMID 35265105, 2022).
cancer (6 papers, 2022 to 2026). A tumor composed of atypical neoplastic, often pleomorphic cells that invade other tissues. "Based on our results, POLE4 can serve as a target to enhance the sensitivity of cancer cells to the combination of PARPi and ATRi." (PMID 38828775, 2024). "But the WWOXP282A mutant protein fails to bind to POLE4, preventing the accurate repair of DNA breaks and ultimately leading to genomic instability and increased cancer risk." (PMID 41124647, 2026). "In line with such a functional relationship, POLE3, POLE4, DSCC1, CHTF18, and CHTF8 show a high correlation in co-essentiality score across cell lines as determined by the Cancer Dependency Map database." (PMID 36622344, 2023).
tumor (5 papers, 2018 to 2023). "They found that miR-519 inhibits the growth and survival of tumor cells via repressing the expression of proteins involved in DNA maintenance (including DUT1, EXO1, RPA2, and POLE4) and intracellular calcium homeostasis (ATP2C1 and ORAI1)." (PMID 37601663, 2023).
infection (3 papers, 2020 to 2023). The state of being infected such as from the introduction of a foreign agent such as serum, vaccine, antigenic substance or organism. "We then generated HeLa cells with knockout (KO) of POLE3 and POLE4 using CRISPR-Cas9 gene editing and measured uHIV-1 DNA expression upon infection with HIV-Luc IND116A virus." (PMID 37922361, 2023). "Our data suggest that the accessory components (RFC2, RFC3, RFC5, PCNA), polymerases (POLD1, POLD2, POLD3, POLE, POLE2, POLE4), and ligase LIG1, were downregulated during infection, for which the downregulation of RFC5, POLD1, POLD2, POLD3, POLE, and LIG1 was CagA-related." (PMID 33339161, 2020).
POLE4 also shares sentences with these, for which no sentence is quoted: Thrombocytosis (2 papers); IMAGe syndrome (1); leukemia (1); malignant mesothelioma (1); neurological diseases (1).